BRCA1 (BRCA1 DNA repair associated)
Diseases named in the same sentence as BRCA1 in open-access papers (continued):
Sharing a sentence is not in itself a finding about the gene and the disease.
ovarian carcinoma (continued). "Previous studies suggested that XRCC3 rs861539, XRCC2 rs718282, XRCC2 rs3218536, BRCA1 rs1799950, RAD51 rs1801320 and LIG4 rs10131 were associated with the risk of ovarian cancer." (PMID 38890669, 2024). "For example, mutations in the BRCA1 and BRCA2 genes serve as important biomarkers for breast and ovarian cancers." (PMID 39767657, 2024). "The collected information highlights the significant role of BRCA1 and BRCA2 mutations in families with a history of two or more cases of ovarian cancer." (PMID 38391958, 2024). "For BRCA1/2 there was a definite increase in the proportion of index cases with ovarian cancer only and pre-symptomatic index tests both doubling from 16 to 32% and 3.2 to > 8% respectively." (PMID 38478259, 2024). "The overexpression of miR-622 in BRCA1-mutant breast and ovarian cancer cell lines MDA-MB436 and UWB1.289 induced resistance to the PARPis olaparib and veliparib as well as to platinum chemotherapy." (PMID 39796639, 2024). "The protein product of the BRCA1 gene is well established as a tumour suppressor, principally of breast and ovarian cancer." (PMID 38149669, 2024). "Our study aims to assess the association between blood iodine levels and the risks of breast and ovarian cancer in a prospective study of healthy BRCA1 carriers." (PMID 38892720, 2024). "Jolie’s announcement drew widespread attention to the BRCA1 and BRCA2 gene mutations, which greatly elevate the risk of breast and ovarian cancer." (PMID 39767657, 2024). "Chenet al discovered that miR-9 mediates the suppression of BRCA1 and hinders DNA damage repair in ovarian cancer cells." (PMID 38433576, 2024). "In the mid-1990s, BRCA1 and BRCA2 gene variants, exposing individuals to a higher risk of breast and ovarian cancer, were discovered." (PMID 39001389, 2024). "Although BRCA1 and BRCA2 mutations are recognised as well-known risk factors for ovarian cancer, they only account for a subset of cases." (PMID 39727715, 2024). "One of the underlying characteristics of Fanconi anaemia is a predisposition to cancer due to increased levels of genomic instability, and BRCA1 and BRCA2 mutations are known to predispose individuals to breast and ovarian cancers." (PMID 38711848, 2024). "The risk of ovarian cancer in this group of patients varies from 27% to 44% in the BRCA2-mutated and BRCA1-mutated patients, respectively." (PMID 38275400, 2024). "The association of BRCA1 and BRCA2 mutations with increased risk for developing epithelial ovarian cancer is well established." (PMID 39028933, 2024). "BRCA1 c.5329dup is one of the more common BRCA1 PVs observed in Romanian patients with breast and ovarian cancer." (PMID 39796670, 2024). "The SOLO2 trial evaluated olaparib maintenance therapy in patients with platinum-sensitive BRCA1 or BRCA2 mutations and relapsed ovarian cancer." (PMID 39590126, 2024). "Genetic factors play a significant role; in particular, 72% of BRCA1 and 69% of BRCA2 mutation carriers have a higher risk of developing breast or ovarian cancers by the age of 80 years." (PMID 38543119, 2024). "Our objective is to identify molecular pathways that are differentially regulated upon the loss of BRCA1 and BRCA2 functions in ovarian cancer." (PMID 39028933, 2024). "A previously reported pathogenic variant was found in BRCA1 (OMIM 113705) (c.181T>C; ClinVar VCV000017661.97) in patient KTWW, which is implicated in breast and ovarian cancer (OMIM 604370)." (PMID 38102329, 2024). "These were all theories until 2014, when OLP, the first PARP inhibitor based on the synthetic lethal mechanism, was approved for the treatment of ovarian cancer with BRCA1 gene defects, with good results." (PMID 38009603, 2024).
ovarian carcinoma (continued). "A panel of HRD and HRP cells (including matched BRCA1 or 2 mutant and corrected pairs) and ovarian cancer ascites cells were used." (PMID 38965423, 2024). "Our custom gene panel resulted in newly identified P/LP findings for 21% of the tested population, with 13% of P/LP findings specific to ovarian cancer (including BRCA1/2 and ATM)." (PMID 39061202, 2024). "For the first time, this study reports the potential role of the BRCA1 foci score to identify HRD ovarian carcinomas." (PMID 38989145, 2024). "PARPi have demonstrated excellent potential in clinical settings, especially when administered to patients with BRCA1 and BRCA2-associated breast and ovarian cancer." (PMID 38993666, 2024). "After recognizing the role that BRCA1 and BRCA2 genes have in susceptibility and prognostic evaluation in breast and ovarian cancer, several works have studied the association between aberrations of DNA-repair system genes and prostate cancer." (PMID 39335746, 2024). "Cancer-predisposing germline gene mutations, mostly in BRCA1 and BRCA2, are better linked to breast and ovarian cancers." (PMID 39061183, 2024). "Prior studies have elucidated key genes in the HR pathway, including, BRCA1, BRCA2, RAD51, and PALB2, that commonly have pathogenic germline variants and/or somatic mutations in breast and ovarian cancers." (PMID 39040162, 2024). "The percentage of respondents associating BRCA1 and BRCA2 mutations with breast and ovarian cancer increased with age group (3.23–6.98–9.09%, p < 0.0108)." (PMID 39728052, 2024). "A more recent meta-analysis and the last published data verified these findings, reporting ovarian cancer risks of 40% for BRCA1 carriers and 18% for BRCA2 carriers." (PMID 38391958, 2024). "The Phase II MEDIOLA study of durvalumab plus olaparib in PARPi-naive patients with germline BRCA1/2-mutant platinum-sensitive recurrent ovarian cancer showed a 72% ORR, median duration of response of 10.2 months, and median PFS of 11.1 months." (PMID 38971950, 2024). "Germline pathogenic genetic variants in the BRCA1 and BRCA2 genes are the most frequent causes of familial breast and ovarian cancer." (PMID 40225940, 2024). "Carriers of BRCA1 and BRCA2 mutations, who are unable to perform effective homologous recombination repair, face significantly increased risks of breast and ovarian cancers." (PMID 39456709, 2024). "Inherited mutations in MMR represent the second most common cause of hereditary ovarian cancer, after BRCA1/BRCA2 mutations, and underlies the Lynch syndrome that predisposes to colorectal, endometrial, and ovarian cancers." (PMID 39492835, 2024). "Our investigation revealed the most common mutations in the BRCA1 and BRCA2 genes associated with breast and ovarian cancer." (PMID 38785549, 2024). "The activation of canonical Wnt/β-catenin signaling in ovarian cancer cells with functional BRCA1 and BRCA2 can confer protumor advantages such as proliferation, survival, and mitochondrial efficiency." (PMID 39028933, 2024). "Its principal objective is to enhance research endeavors and methodologies for the classification of variants in BRCA1, BRCA2, and additional genes associated with breast and ovarian cancer susceptibility." (PMID 38397209, 2024). "Some of the reported hypermethylated genes in ovarian cancer are BRCA1, RASSF1A, TGFBI, DOK1, RUNX3, and CAMK2N1." (PMID 38627856, 2024). "Out of the 132 BRCA1-methylation-positive breast and ovarian cancer cases, the family history was known for only 75 cases." (PMID 38542081, 2024).
ovarian carcinoma (continued). "A recent study showed that paclitaxel inhibits CDK1, resulting in weakened BRCA1 phosphorylation, which sensitizes ovarian cancer cells with proficient homologous recombination to PARP inhibitors." (PMID 38433576, 2024). "Carriers of BRCA1 and BRCA2 pathogenic variants have lifetime risks of ovarian cancer and fallopian tube cancer of 40–60% and 15–30%, respectively." (PMID 38256099, 2024). "In order to study the possible role of PAR2/f2rl1 in the etiology of ovarian cancer, we have undertaken the task of evaluating levels of PAR2 expression in FTs of normal and high-risk carriers of BRCA1/2 mutations." (PMID 38275417, 2024). "The key HR genes, BRCA1 and BRCA2, are particularly significant as their germline pathogenic variants are associated with a hereditary predisposition to breast and/or ovarian cancer." (PMID 39080120, 2024). "Within the 2022 ELN AML diagnostic criteria, in the separate “AML with germline predisposition” category, it is highlighted that the BRCA1 and BRCA2 inherited mutations predispose not only to myeloid neoplasms but also to BC and ovarian cancers." (PMID 38398301, 2024). "Lastly, annotating samples as HRD and HRP based on defects in BRCA1/2 genes provided separation in progression free survival for the 25 PARPi-treated ovarian cancers." (PMID 39040162, 2024). "The ovarian cancer incidences for BRCA2 carriers were lower compared to BRCA1 carriers (incidences per 1000 person-years increased from 2 at age 60 to 11 at age 80)." (PMID 38333895, 2024). "Our results show that Wnt3A upregulates canonical β-catenin targets in ovarian cancer cells with functional BRCA1 and BRCA2, particularly the full-length WT Tcf1/7, c-Myc, and cyclin D1." (PMID 39028933, 2024). "Women with a PV in BRCA1 and BRCA2 have a lifetime risk of 35–45% and 10–20% for ovarian cancer, respectively." (PMID 38907139, 2024). "Germline mutations in BRCA1 and BARD1 are the main cause of hereditary breast and ovarian cancers, conferring a life-time probability of up to 90% for developing breast cancer and 50% for ovarian cancer." (PMID 38769345, 2024). "In this paper, we show that a high blood lead level is a marker for ovarian cancer in BRCA1 carriers." (PMID 38732616, 2024). "Premenopausal BRCA1/2-pV carriers or carriers of pV in other breast and/or ovarian cancer genes or genes of the Lynch-syndrome should be offered HRT after RRSO to counteract negative effects of estrogen deficiency." (PMID 39259360, 2024). "In previous studies of ovarian cancer in China, the carrying rates of BRCA1 were generally higher than our results." (PMID 38817903, 2024). "Women with inherited mutations in BRCA1 or BRCA2 face an elevated risk of developing breast and ovarian cancers." (PMID 39742378, 2024). "Clearly, more research is needed to characterize interactions between BRCA1 epimutation status and therapy sensitivity in breast as well as ovarian cancer." (PMID 40225940, 2024). "After BRCA1 and BRCA2, FANCJ is the third most common ovarian cancer susceptibility gene: nearly 0.9– 2.5% of all ovarian cancer patients carry a splice-site, stop, or frameshift mutation in the FANCJ gene." (PMID 38177925, 2024). "Deficiency in homologous recombination repair (HRD) characterizes almost half of high-grade ovarian carcinomas and is due to genetic and epigenetic alterations in genes involved in HR repair, mainly BRCA1/BRCA2, and predicts response to PARPi." (PMID 38989145, 2024).
ovarian carcinoma (continued). "By providing a comprehensive understanding of the BRCT domain of BRCA1, this review aims to shed light on the role of this important domain in the pathogenesis and potential therapeutic approaches for breast and ovarian cancer." (PMID 38543119, 2024). "Actionable BRCA1/2 mutations detected by NGS were not limited to breast and ovarian cancer, but were observed in several tumor types (e.g. colorectal cancer, glioblastoma, head and neck cancer, pancreatic adenocarcinoma, prostate cancer)." (PMID 38800398, 2024). "The Couch model was designed to provide probability estimates for the detection of BRCA1 PGVs in women with a family or personal history of BC, ovarian cancer, or both." (PMID 38672070, 2024). "Mutations in DDR molecules, particularly FA genes (e.g., PALB2) and BRCA genes (e.g., BRCA1) can lead to significant complications, including breast/ovarian cancer and severe forms of Fanconi anemia." (PMID 39199310, 2024). "Using the SL concept, four poly (ADP-ribose) polymerase (PARP) inhibitors have been approved by the FDA for the treatment of BRCA1/2-mutant breast and ovarian cancers." (PMID 38348889, 2024). "Changes due to mainstreaming has also changed the cancers from which index cases have suffered, with ovarian cancer becoming more frequent in BRCA1/2 and endometrial cancer in Lynch syndrome." (PMID 38478259, 2024). "Compared with sporadic epithelial ovarian cancer (EOC) patients, both BRCA1 and BRCA2 associated patients have improved outcomes after primary therapy, including chemotherapy." (PMID 38561819, 2024). "Penetrance estimated by age of 70 years for ovarian cancer was 48.3% and 20.0% for BRCA1 and BRCA2, respectively." (PMID 38524651, 2024). "In the Chinese population, BRCA1 c.2566 T > C was more frequent in ovarian cancer patients than healthy controls." (PMID 38509102, 2024). "BRCA1 and BRCA2 mutations are responsible for a higher incidence of breast and ovarian cancer (from 55% up to 70% vs. 12% in the general population)." (PMID 38792636, 2024). "Our investigation indicates the most common mutations in the BRCA1 and BRCA2 genes, associated with breast and ovarian cancer in the Romanian population." (PMID 38785549, 2024). "The activation of canonical Wnt signaling in ovarian cancer cells with functional BRCA1 and BRCA2 can also directly promote resistance to PARP inhibitors." (PMID 39028933, 2024). "This study reports for the first time the capacity of the BRCA1 foci test to identify HRD ovarian carcinomas and possibly predict response to olaparib." (PMID 38989145, 2024). "Clinical management of Asian BRCA1 and BRCA2 pathogenic variants (PV) carriers remains challenging due to imprecise age-specific breast (BC) and ovarian cancer (OC) risks estimates." (PMID 38333895, 2024). "The objective response rate was the highest, at 63% amongst BRCA1/2-altered platinum-sensitive ovarian cancer patients, and a prolonged duration of response of 11.1 months identified for TNBC patients." (PMID 39201718, 2024). "In the case of BRCAness tumors (found in breast, prostate, pancreatic, or ovarian cancer), most germline BRCA1/2 mutants are biallelically inactivated, indicating their sensitivity to PARP inhibitors." (PMID 38895905, 2024). "BRCA1 (MIM# 113705), a tumor suppressor gene located on chromosome 17q21, plays an important role in breast and ovarian cancer risk/development." (PMID 38892720, 2024). "In the current study, ten family members carried the BRCA1 variant, four developing CRC with only three developing a breast or ovarian cancer." (PMID 38063999, 2024). "For example, BRCA1 and BRCA2 mutations are associated with an increased risk of second primary breast or ovarian cancer." (PMID 38770671, 2024). "A recent study demonstrated that the loss of RBM39 induces splicing defects in key DNA damage repair genes, such as ATM and BRCA1, in ovarian cancer, leading to increased sensitivity to cisplatin and various PARPi18." (PMID 38789724, 2024).
ovarian carcinoma (continued). "Compared with the general population, female carriers of BRCA1 and BRCA2 mutations exhibit an increased lifetime risk of developing breast and ovarian cancer by 59% and 16.5%, respectively." (PMID 39201170, 2024). "BRCA1 mutation patients are more common in C3, while BRCA2 mutation patients are mostly ovarian cancer C2-subtype, each having different prognoses." (PMID 38543119, 2024). "Individuals with pathogenic variants of BRCA1 and BRCA2 are at higher risk of breast and ovarian cancers." (PMID 39507757, 2024). "Despite their common roles in DNA repair, several clinical distinctions have been observed between BRCA1 and BRCA2 mutation carriers in the context of ovarian cancer." (PMID 39028933, 2024). "The prevalence of germline BRCA1/2 PVs in this meta-analysis was higher than expected in an unselected population of women with ovarian cancer." (PMID 39550490, 2024). "Epithelial ovarian cancers that harbour a germline BRCA1/2 PV respond better radiologically to platinum-based chemotherapy compared to those with germline BRCA1/2 wild type." (PMID 39550490, 2024). "In conclusion, PARP inhibitors represent a significant advancement in treating advanced ovarian cancer, offering an encouraging medical alternative, especially for BRCA1/2 mutants and patients with HR defects." (PMID 39360040, 2024). "Senataxin cooperates with the breast and ovarian cancer BRCA1 protein in the removal of R-loop-driven DNA damage at transcribed genes and was found down-regulated in a range of cancer types, including ovarian cancer, suggesting a tumor suppressor activity." (PMID 39120648, 2024). "The PRIMA/PRIME and NOVA/NORA clinical studies demonstrated significant clinical efficacy of niraparib in patients with BRCA1/2 mutant ovarian cancer." (PMID 38798714, 2024). "The only two genes with more than 2% of patients having germline mutations were BRCA1 and BRCA2 in ovarian cancer (5.3% and 2.8% respectively)." (PMID 39277826, 2024). "We conducted a comprehensive analysis of a group of 1958 Saudi women, comprising breast and ovarian cancer patients and controls, to determine the prevalence of BRCA1 and MGMT epimutations." (PMID 38542081, 2024). "Inherited BRCA1 and BRCA2 variants are the main known cause of hereditary breast and ovarian cancer cases." (PMID 38195559, 2024). "For example, sequencing the BRCA1 and BRCA2 genes can screen high-risk groups for hereditary breast and ovarian cancer, enabling early diagnosis and prevention." (PMID 39872399, 2024). "BRCA1 and BRCA2 are the most studied ovarian cancer susceptibility genes, and are associated with hereditary breast and ovarian cancer syndrome." (PMID 38509102, 2024). "Mutations in the BRCA1 and BRCA2 genes are known and significant risk factors for breast and ovarian cancer." (PMID 39728052, 2024). "Women carrying BRCA1 and BRCA2 pathogenic variants have a significant lifetime risk of breast and ovarian cancers, with rates of up to 85% and 65%, respectively." (PMID 39061189, 2024). "Vietri and coworkers described 2 families with DH PSV in BRCA1 and BRCA2 and concluded that earlier age at BC diagnosis (32 years) and ovarian cancer diagnosis (36 years) imply that the phenotype is more severely affected by the BRCA1 PSV." (PMID 39102164, 2024). "In this study, we sought to identify molecular pathways that are differentially regulated in the context of BRCA1 and BRCA2 mutations in ovarian cancer." (PMID 39028933, 2024).